RN7SL331P (RNA, 7SL, cytoplasmic 331, pseudogene)
Gene: Miscellaneous RNA gene on chromosome 15 (84,205,454 to 84,205,700, reverse strand). Ensembl gene ENSG00000278422.
Homologues: Orthologues: chimpanzee Metazoa_SRP (80% identical), macaque Metazoa_SRP (36% identical), macaque Metazoa_SRP (32% identical). Paralogues in human: Metazoa_SRP (100% identical), RN7SL428P (100% identical), RN7SL417P (70% identical), RN7SL736P (68% identical), RN7SL214P (68% identical), RN7SL319P (68% identical), Metazoa_SRP (66% identical), RN7SL241P (66% identical), RN7SL536P (65% identical), Metazoa_SRP (65% identical), RN7SL106P (65% identical), RN7SL209P (65% identical), and 707 more.